IL18 (interleukin 18)
Description:
Pro-inflammatory cytokine primarily involved in epithelial barrier repair, polarized T-helper 1 (Th1) cell and natural killer (NK) cell immune responses. Upon binding to IL18R1 and IL18RAP, forms a signaling ternary complex which activates NF-kappa-B, triggering synthesis of inflammatory mediators. Synergizes with IL12/interleukin-12 to induce IFNG synthesis from T-helper 1 (Th1) cells and natural killer (NK) cells. Involved in transduction of inflammation downstream of pyroptosis: its mature form is specifically released in the extracellular milieu by passing through the gasdermin-D (GSDMD) pore.
Synonyms: IL-18; IGIF; IL1F4; IL-1g
Tractability: Antibody: a drug acting on it is in phase 2 or 3 trials; UniProt places it where antibodies can reach, with high confidence; its Gene Ontology location is reachable by antibodies, with high confidence. PROTAC: ubiquitination databases record sites on it; its protein half-life has been measured; a small molecule that binds it is known. Other modalities: a drug acting on it is in phase 2 or 3 trials.
Target class: Secreted protein
Gene: Protein-coding gene on chromosome 11 (112,143,251 to 112,164,106, reverse strand). Ensembl gene ENSG00000150782.
Subcellular location: Cytoplasm, cytosol; Secreted
Subcellular location (Human Protein Atlas): Golgi apparatus; Nucleoplasm; Cytosol; Predicted to be secreted
Pathways (Reactome):
Immune System: CASP4-mediated substrate cleavage; CASP5-mediated substrate cleavage; Interleukin-1 processing; Interleukin-10 signaling; Interleukin-18 signaling; Interleukin-4 and Interleukin-13 signaling
Disease: Purinergic signaling in leishmaniasis infection
Programmed Cell Death: Pyroptosis
Gene Ontology:
Molecular function: cytokine activity; interleukin-18 receptor binding; protein binding; receptor ligand activity
Biological process: angiogenesis; interleukin-18-mediated signaling pathway; positive regulation of activated T cell proliferation; positive regulation of granulocyte macrophage colony-stimulating factor production; positive regulation of interleukin-17 production; positive regulation of natural killer cell proliferation; positive regulation of NK T cell proliferation; positive regulation of phosphatidylinositol 3-kinase/protein kinase B signal transduction; positive regulation of smooth muscle cell proliferation; positive regulation of T-helper 1 cell cytokine production; positive regulation of transcription by RNA polymerase II; positive regulation of type II interferon production; positive regulation of tyrosine phosphorylation of STAT protein; regulation of cell adhesion; T-helper 1 type immune response; cell-cell signaling; cellular response to lipopolysaccharide; cholesterol homeostasis; cytokine-mediated signaling pathway; defense response to Gram-positive bacterium; establishment of skin barrier; immune response; inflammatory response; negative regulation of T-helper 1 type immune response; positive regulation of chemokine production; and 13 more
Cellular component: decoy receptor complex; extracellular region; interleukin-18 receptor complex; cytosol
Genetic constraint (gnomAD): Loss-of-function variants: 0 observed, 0.29 expected, observed/expected ratio (o/e) 0, 90% interval 0 to 1.87. That is too few expected variants to judge how well the gene tolerates losing a copy. Missense variants: 11 observed, 19.07 expected, observed/expected ratio (o/e) 0.58, 90% interval 0.36 to 0.95. Synonymous variants: 5 observed, 7.65 expected, observed/expected ratio (o/e) 0.65, 90% interval 0.34 to 1.36.
Homologues: Orthologues: chimpanzee IL18 (100% identical), macaque IL18 (94% identical), pig IL18 (75% identical), dog IL18 (73% identical), guinea pig IL18 (68% identical), mouse Il18 (64% identical), rat Il18 (63% identical).
Diseases named in the same sentence as IL18 in open-access papers:
IL18 is named in the same sentence as 894 diseases in open-access papers, as found by Europe PMC text mining. Sharing a sentence is not in itself a finding about the gene and the disease. The quoted sentences say what the papers report.
COVID-19 (351 papers, 2020 to 2026). A disease caused by infection with severe acute respiratory syndrome coronavirus 2. "On the other hand, IL-18 hyper-responsiveness has been implicated as a contributory factor to the cytokine storm and increased mortality in conditions such as sepsis and Coronavirus Disease 2019 (COVID-19)." (PMID 40661891, 2025). "Collectively, these findings support a central role for IL-18 in COVID-19 pathogenesis and underscore its association with disease severity and adverse outcomes." (PMID 40788382, 2025). "COVID-19 is also associated with high levels of proinflammatory cytokines such as interleukin-6 (IL-6), IL-1B, IL-18, and granulocyte-macrophage colony-stimulating factor, a state commonly referred to as “cytokine storm”." (PMID 40066309, 2025). "Protein levels of SLAMF1, IL15RA, and IL18 associated with critical illness during the acute phase of COVID-19 also predicted Long COVID risk." (PMID 40475767, 2025). "IL-18 is a proinflammatory cytokine that appears to play a role in the cytokine storm and hyperinflammation associated with severe COVID-19 cases." (PMID 40552037, 2025). "Inflammasome and pyroptosis signalling have been implicated in the pathogenesis of COVID-19 because of their known link to the release of bio-active IL-1β and IL-18." (PMID 40016339, 2025). "Despite mild/no symptoms, significantly elevated cytokine levels, including IL-6, INF-γ, MCP-1, and IL-18 were observed in COVID-19+ pregnancies, associated with distinct hemostasis alterations." (PMID 40303405, 2025). "During SARS-CoV-2 infection, activation of the NOD-like receptor family pyrin domain-containing 3 (NLRP3) inflammasome pathway is thought to contribute to the release of bioactive IL-1β and IL-18, cytokines associated with severe COVID-19." (PMID 40016339, 2025). "This hyperinflammatory state and the elevated levels of IL-18 have been associated with disease severity and poor outcomes in severe COVID-19 cases." (PMID 40788382, 2025). "Our results showed that 2 inflammatory proteins (interleukin-10 and interleukin-18) were positively associated with COVID-19 risk, while 1 inflammatory protein (PD-L1) was negatively associated." (PMID 40101060, 2025). "Others showed positive associations between salivary viral load (VL) and COVID-19-related pro-inflammatory markers; IL-6, IL-18, IL-10, and CXCL1028." (PMID 39294156, 2024). "In particular, the association between ferritin, soluble CD163, IL-18, and COVID-19 prognosis was assessed." (PMID 38398719, 2024). "IL-18 was identified as one of the biomarkers of a cytokine storm signature, including that of COVID-19, and was associated with disease severity." (PMID 39769266, 2024). "In severe cases of COVID-19, circulating iNKT cells have been shown to be activated by IL-18, which is a cytokine associated with unconventional T cell activation during viral infections in general." (PMID 38321023, 2024). "This is in line with the high levels of IL-18 found to be associated with disease severity and poor clinical outcome in COVID-19 patients." (PMID 38983847, 2024). "The expression of caspase-4 in the lungs of COVID-19 patients showed an association with the levels of inflammasome activation markers such as caspase-1, IL-1β, IL-6 and IL-18." (PMID 37251383, 2023). "In fact, IL-18 was one of the top cytokines to discriminate mortality associated with COVID-19 among a survey of 19 cytokines after multi-variate adjustment." (PMID 36894537, 2023). "There are many papers explaining role of IL-6 and its polymorphism in prediction severity and mortality of COVID-19, but there are few papers regarding role of IL-18 SNP in prediction mortality of the disease." (PMID 36999046, 2023). "One study reported an association between serum levels of IL-18 and mortality and morbidity of hospitalized COVID-19 patients." (PMID 37582864, 2023). "This study evaluated the association of polymorphisms of - 607 SNP of IL-18 with COVID-19 mortality among the Kurdish population." (PMID 36999046, 2023).
COVID-19 (continued). "Consistent with prior reports, IL-6, well-known to associate with poor survival during COVID-19, IL-27, and IL-15 were also observed to stratify survival, but IL-6 displayed a lower hazard ratio than IL-18." (PMID 36894537, 2023). "According to our knowledge, no article has examined the association between the -607 T/G SNP of the IL-18 gene and mortality in COVID-19." (PMID 36999046, 2023). "Elevated free IL-18 levels from symptom day 15 onwards are associated with COVID-19 severity and mortality." (PMID 36823262, 2023). "Further supporting these associations from circulating blood levels, Patients with COVID-19 exhibited elevated IL-18 and IL-15 expression in their lung tissues compared with control patients without COVID-19." (PMID 36894537, 2023). "Studies indicate that the potential activation of the NLRP3 inflammasome by SARS-CoV-2 directly leads to elevated levels of pro-inflammatory cytokines IL-1β and IL-18 in severe COVID-19 patients, which are associated with adverse outcomes." (PMID 38193087, 2023). "Based on known associations between inflammasome activation and cardiovascular and pulmonary outcomes, our findings suggest a critical role of abnormal expression of IL-18 during COVID-19-associated cardiopulmonary damage." (PMID 36894537, 2023). "Acute COVID-19 was associated with marked elevations in nearly all pro-inflammatory markers, whilst eleven markers (namely IL-1β, IL-2, IL-6, IL-10, IL-18, IL-23, IL-33, TNF-α, IP-10, G-CSF and YKL-40) were associated with disease severity." (PMID 37063871, 2023). "In previous studies, the JAKs/STAT3 for signal transduction can activate pro-inflammatory gene expressions and facilitate the NLRP3 inflammasome to secrete IL-1β and IL-18 during the pathogenesis of COVID-19-associated neurodegenerative diseases." (PMID 36698809, 2022). "In mice, IL-18 in vivo administration caused NK cell and T cell activation in the heart and mild cardiac dysfunction, replicating our findings in the patient with COVID-19 vaccine-related myopericarditis." (PMID 35251049, 2022). "In this study, we found ddcfDNA was significantly elevated in SOTRs with COVID-19 and strikingly correlated with cytokines/chemokines (IL-10, IL-8, IL-2Ra, IL-18, GM-CSF and IL-12p70) associated with CRS." (PMID 35075453, 2022). "In moderate COVID-19 patients, the diagnostic performance was fair (acceptable) for IL-Iβ, IL-4, IL-18 and IL-35 because the AUC values ranged between 0.7–0.8." (PMID 36675695, 2022). "Using the same cohort, we found that IL-18 and IL-18BP concentrations show a suggestive positive association with the genetic risk of COVID-19." (PMID 35634344, 2022). "Higher levels of Casp1p20 and IL-18 which are inflammasome-derived products in the sera were found associated with COVID-19 severity and poor clinical outcome, including IL-6 and lactate dehydrogenase." (PMID 35582503, 2022). "It is important to underline that prolonged activation of NLRP3 leads to an increase in the levels of IL-1β and IL-18 which are associated with more severe forms of COVID-19." (PMID 35566589, 2022). "In contrast, the dysregulated induction of inflammasomes, leading to uncontrolled production of IL-1 family cytokines (IL-1β and IL-18) and pyroptosis, has been associated with COVID-19 pathogenesis." (PMID 35336937, 2022). "In severe COVID-19 patients, the diagnostic performance was good for IL-6 (AUC = 0.844), fair (acceptable) for IL-18 (AUC = 0.785) and IL-35 (AUC = 0.742), and poor for IL-1β (AUC = 0.604)." (PMID 36675695, 2022). "Perhaps unexpectedly, several cytokines associated with severe COVID-19 and damaging cytokine overproduction (IL-6, IL-15, and IL-18) were reduced following coinfection at 5 d pvi." (PMID 35634338, 2022). "Immune dysregulation, a hallmark of COVID-19 course and severity, is mainly orchestrated by cytokines and chemokines (e.g., IL-6, IL-1β, IL-8, IL-18, TNF-a) that are identified as tumorigenesis drivers." (PMID 36298472, 2022).
COVID-19 (continued). "There has been evidence that circulating iNKT cells are activated by IL-18 in severe cases of COVID-19, IL-18 cytokine is associated with T cell activation during viral infections." (PMID 36034704, 2022). "Levels of four cytokines (IL-6, IL-10, IL-18, IL-27) were consistently elevated in patients with COVID-19 independently of the variant." (PMID 36430621, 2022). "The serum concentrations of IL-18 correlate with other inflammatory markers and are linked to the severity of COVID-19." (PMID 35930243, 2022). "In severe cases of COVID-19, circulating iNKT cells have been shown to be activated by IL-18 which is a cytokine associated with unconventional T cell activation during viral infections." (PMID 34050887, 2022). "The processing and release of IL-18, which is dependent on the activation of the inflammasome and gasdermin D, has been linked with severe COVID-19 and has emerged as a highly predictive biomarker of mortality." (PMID 35336937, 2022). "The inflammatory cytokine profile of Pso patients at risk for COVID-19 included in our study showed increased levels of IL-18, IL-17A and IL-6 and decreased levels of IL-27 when compared to HCs." (PMID 34068473, 2021). "Genetically predicted interleukin-18 was associated with lower risk of any COVID-19 (odds ratio (OR) 0.96 per standard deviation, 95% confidence interval (0.94–0.99, P-value 0.004)) and of very severe COVID-19 (OR 0.88, 95% CI 0.78–0.999, P-value 0.048)." (PMID 34911594, 2021). "Findings on renal injury in cases of COVID-19 and its association with IL-18 will also be presented." (PMID 33732720, 2021). "Using a more liberal selection of genetic variants (P-value <5 × 10−6) interleukin-18 remained associated with any COVID-19 using IVW; the weighted median and MR-Egger estimates were similar." (PMID 34911594, 2021). "IL-6 >142.5 pg/mL, IL-10 >10.8 pg/mL, IL1β > 4.68 pg/mL, sIL-2rα >804.5 pg/mL, IL-1Ra >88.4 pg/mL, and IL-18 > 144 pg/mL values were associated with the development of critical COVID-19 in the age-adjusted univariate analysis." (PMID 34422145, 2021). "Together, these data suggest a limited contribution of the IL-1β and IL-18 pathways and inflammasome activation to COVID-19–associated clinical outcome." (PMID 33232303, 2021). "Similar to SARS-CoV-1 in 2003, severe/critical COVID-19 was associated with higher levels of Th1 cytokines such as IL-18, IP-10, and MIG." (PMID 34938289, 2021). "For example, in Coronavirus-related publications, diarrhea, one of the reported symptoms of COVID-19, is associated with IL-18, monocytes, T-lymphocytes, dendritic cells and erythrocytes." (PMID 32746922, 2020). "In contrast, pro-inflammatory cytokines and chemokines, including CCL14, CCL23, IL7, IL16 and IL18, were preferentially expressed in men, underlying the higher susceptibility of men developing cytokine release syndrome in COVID-19." (PMID 32974111, 2020). "Several studies reported an association between IL-1β and IL-18 serum levels and severe COVID-19." (PMID 40016339, 2025). "Furthermore, several studies confirm that severe immune dysregulation during COVID-19 progression, along with inflammasome-associated cytokines such as IL-1β and IL-18, is significantly associated with vascular damage." (PMID 41357188, 2025). "Notably, baseline protein levels of SLAMF1, IL15RA and IL18 associated with the critical illness during the acute phase of COVID-19 were also able to predict Long COVID risk." (PMID 40475767, 2025). "It has been suggested that IL-18 is associated with a lower risk of developing severe COVID-19." (PMID 38540716, 2024). "Both patients with active AOSD or with severe coronavirus disease-2019 showed elevated Gal-3 and cytokines, including IL-1β, IL-6, and IL-18, supporting a common link of cytokine storm in their pathogenesis." (PMID 38711500, 2024).
COVID-19 (continued). "Also, COVID-19 can cause immunosuppression or cytokine release, which can increase the risk of fungal infections with increased IL-18, IL-17, IL-33, neutrophils, monocytes, and basophils." (PMID 38747876, 2024). "IL-18 might protect against COVID-19, but IL-18 hypercytokinemia is associated with an increased severity of COVID-19." (PMID 39431236, 2024). "Mechanisms of IL-18 activation appear to involve mitophagy blockade and ROS release, highlighting mitophagy and ROS as additional novel potential therapeutic targets for COVID-19-associated cardiopulmonary manifestations." (PMID 36894537, 2023). "One of the principal findings of our study was that the IL18-rs1834481 polymorphism appeared to have a strong impact on COVID-19 clinical outcome, since heterozygotes for the rs1834481 polymorphism were at a higher risk of developing pneumonia (both in univariate and multivariate analyses)." (PMID 37766191, 2023). "There is evidence that the severity of COVID-19 is linked to high levels of IL-18 in the blood." (PMID 36999046, 2023). "Our work suggests that targeting inflammasome-dependent IL-1β/IL-18 and/or purinergic signaling pathways may offer a novel opportunity for the treatment of viral infection and hyper-inflammation associated with COVID-19." (PMID 37920468, 2023). "In one study of COVID-19 cases, high serum IL-18 was associated with worse outcomes." (PMID 36992320, 2023). "One study correlated the level of IL-18 determined from a genome-wide association study (GWAS) was protective against severe COVID-19, and the authors suggested that IL-18 could participate in producing IFN-γ." (PMID 37398192, 2023). "The result of the increase in the serum concentration of IL-18 is relevant, since myo-pericarditis following COVID-19 mRNA vaccination may be associated with increased IL-18-mediated immune responses and cardiotoxicity." (PMID 37112659, 2023). "Proinflammatory cytokines and acute-phase reactants such as IL-1β and IL-18 caused by COVID-19 around NLRP3 activation may directly or indirectly cause inflammation and pancreatic β cell damage, resulting in severe insulin resistance and hyperglycemia." (PMID 37868953, 2023). "IL-6 and IL-18 may each contribute various aspects of these COVID-19-linked perturbations, according to a screen for potential agents." (PMID 36992283, 2023). "Furthermore, an elegant longitudinal study performed in patients with COVID-19 found a correlation between the late-stage pathology in COVID-19 and cytokines linked to the inflammasome pathway, including IL-1β and IL-18." (PMID 37113134, 2023). "Collectively, myopericarditis following COVID-19 mRNA vaccination may be associated with increased IL-18-mediated immune responses and cardiotoxicity." (PMID 35251049, 2022). "We sought to investigate the potential role of LIGHT and IL18 in bacterial- and viral-induced sepsis unrelated to COVID-19, and specifically the proteins’ associations with ARDS, acute hypoxic respiratory failure, and AKI as major sepsis complications in 280 patients with sepsis." (PMID 35203474, 2022). "We found that recombinant IL-18 administration into mice caused mild cardiac dysfunction and activation of NK cells and T cells in the hearts, similar to the findings in the patient with myopericarditis after COVID-19 mRNA vaccination." (PMID 35251049, 2022). "A screen for candidate agents revealed that IL-6 and IL-18 may individually contribute different facets of these COVID-19–linked perturbations." (PMID 34433692, 2021). "Overall, CEC attributes of convalescent COVID-19 patients correlated with a vast majority of differentiation and activation factors associated with T cells and B cells (IL-4, IL-5, IL-7, IL-17A, IL-18, MIP-1α, and RANTES), implicating a broad adaptive immune response with endothelial dysfunction." (PMID 33752798, 2021).